BRAF (B-Raf proto-oncogene, serine/threonine kinase)
Diseases named in the same sentence as BRAF in open-access papers (continued):
Sharing a sentence is not in itself a finding about the gene and the disease.
melanoma (continued). "As A375 is a BRAF activated cell line, inhibition of BRAF by DETS may be leading to the inhibition of the down-stream molecules Brn-2 and β-catenin that leads to the inhibition of MITF-M, the pivotal molecule regulating the proliferation of melanoma." (PMID 27148169, 2016). "Because BRAF and ERK2 are main components of the RAS-MAPK pathway, the decreased expression of miR-524-5p in melanomas could mediate tumor proliferation and cell migration in melanomas." (PMID 26646588, 2016). "This approach is based on observations such as the development of resistance to B-Raf inhibitors accompanied by an upregulation of PD-L1 on melanoma cells and the influx of TILs in biopsy samples taken soon after the initiation of BRAF-V600E inhibition in patients with melanoma." (PMID 27151159, 2016). "Mutation status was also significantly associated with the site of the primary tumor (P= 0.004, Chi-square test); BRAF and NRAS mutations were relatively more common in melanomas from the trunk (23.6% and 21.0%) compared to tumors without mutations detected (Wild Type) (15.3%)." (PMID 27191502, 2016). "Though possibly the case for primary melanoma, our study has shown that this is not the case when investigating metastatic melanoma, where PAK1 overexpression correlates with invasion (rather than BRAF mutational status)." (PMID 27765920, 2016). "Moreover, there are no viable treatment options available for other non-BRAF melanoma subtypes in the clinic." (PMID 27846237, 2016). "Targeting a hyperactivated MAPK pathway driven by mutated NRAS or BRAF with specific BRAF- and MEK inhibitors, increases the median overall survival from metastasized melanoma patients from 9 months with no therapy to approximately 14 months with successful inhibitor treatment." (PMID 27791198, 2016). "However, MAPKi combination treatment induced cell death and reduced cell numbers in a synergistic manner in BRAF mutant melanoma cell lines, but not in the BRAF mutant/MITF-negative colon cancer cell line RKO." (PMID 26977879, 2016). "In addition, we show that the combination of MEK and BRAF inhibitors is synergistic in BRAF-mutant melanoma cells, and additive or antagonistic in, respectively, BRAF-wild type melanoma cells and non-malignant fibroblasts." (PMID 26018524, 2015). "We developed a novel ranking metric for TOKEn-generated hypotheses for BRAF inhibitor (n=3) and non-BRAF inhibitor (n=39) drug combinations in melanoma." (PMID 26262134, 2015). "We found minimal involvement of the BRAF/MEK pathway irrespective of whether the melanoma cells were resistant to vemurafenib or not." (PMID 25844720, 2015). "Remarkably, among the total 30 BRAF mutations found in melanomas (30/62, 48%), we detected 6 complex mutations (1 p.V600E2, c.1799_1800TG > AA and 5 pV600K, c.1798_1799TG > AA), 20% (6/30) of the BRAF mutations, showing that the frequency of these events is not low." (PMID 26435479, 2015). "It is not indicated for treatment of patients with wild-type BRAF melanoma." (PMID 26431495, 2015). "We observed that treatment of melanoma cells with BRAF inhibitors did not induce Bcl-2 expression." (PMID 26497853, 2015). "Furthermore, the inhibitor of mutant BRAF Dabrafenib, but not Vemurafenib, inhibited necroptosis in melanoma cells whenever RIPK3 is present." (PMID 26355347, 2015). "In recent studies of thyroid carcinoma and melanoma, SPRY2 and SOX10 have been identified as additional BRAF-EGFR feedback mediators, which suggests that feedback signaling of BRAF V600E to the EGFR might be more complex than initially thought and includes other, hitherto unknown proteins as well." (PMID 26065894, 2015). "Melanoma cells, unlike colorectal cancer cells, are sensitive to BRAF inhibitors." (PMID 25885672, 2015). "Moreover, a triple drug combination including inhibitors of BRAF, MEK, and AurkA offered increased efficacy against melanoma cell growth; it might become a potential innovative treatment strategy." (PMID 26322273, 2015).
melanoma (continued). "Vemurafenib has not been tested and is not indicated in patients with wild-type BRAF melanoma." (PMID 26705496, 2015). "In addition, for a large proportion of patients with melanoma—those who have wild-type BRAF—treatment with BRAF inhibitors is not approved by the FDA due to the possibility of disease exacerbation." (PMID 27069772, 2015). "While melanoma cell populations that express high levels of RTK may be selected and expand following MAPK inhibitor treatment, FOXD3 is increased by BRAF inhibitor treatment and transcriptionally induces ERBB3 expression, providing an early adaptive resistance response in melanoma." (PMID 26426052, 2015). "Although acquired resistance to BRAF inhibitors treatment is known to involve reactivation of MAPK signaling, an accumulating body of evidence suggests that activation of PI3K signaling also contributes to intrinsic cascades involved in melanoma development and progression." (PMID 26299806, 2015). "Recently, SCH772984 has been shown to be a selective and potent ERK1/2 inhibitor which preferentially affects cell survival of BRCA2-deficient breast cancer cells, as well as also induces apoptosis and cell cycle arrest in BRAF-mutant or non-BRAF-mutant melanoma." (PMID 25742792, 2015). "These include identification of BRAF target genes by comparing gene expression profiles in melanomas treated with/without BRAF inhibitors, screening for expression of relevant molecules to be targeted by inhibitors, and comparison of gene expression profiles of BRAFV600E vs wild-type tumors." (PMID 25576923, 2015). "The lack of antitumor effect of ZA in vivo on the NRAS mutant and BRAF mutant and PTEN null melanoma cells may be explained by the fact, that around 50–60% of ZA accumulates in the skeleton and the remaining part is excreted in the first 24hs after drug administration." (PMID 25646931, 2015). "We ascertained that there are two possible MEK1/2-inhibitor response “classes” within pan-negative melanomas: Class I pan-negative responders behave like BRAF V600-mutant cells in that they are highly sensitive to MEK1/2 inhibition and downregulation of phosphorylated MEK1/2 and ERK1/2 is observed." (PMID 26084293, 2015). "To expand this analysis, we obtained IC50 values to PLX4720 for 35 melanoma cell lines in the Cancer Cell Line Encyclopedia and plotted the IC50 for each line in order, as well as lines in our study, and colored the bars based on their zygosity status at the BRAF locus." (PMID 26405815, 2015). "These might comprise 4 to 8% of the “pan-negative” melanomas, and, while their growth is not affected by BRAF inhibitors, they are sensitive to MEK inhibitors." (PMID 24743024, 2014). "Interestingly mutBRAF melanoma patients have shown responses to DTIC of up to 23% but, on the other hand, recent reports state that activating mutations in BRAF have no impact on the response of stage IV melanoma patients to DTIC or TMZ." (PMID 24941944, 2014). "In addition to the BRAF-MEK-ERK (MAPK) pathway, the nuclear factor kappa B (NFκB) signaling pathway also plays an important role in cell invasion and is also found to be hyperactivated in variety of cancers including melanoma." (PMID 24466036, 2014). "EGFR is not expressed, in general, by melanoma cells, and in vitro studies concluded that EGFR expression is disadvantageous for BRAFV600E melanoma cells in the absence of BRAF or MEK inhibitor drugs, but it confers a selective advantage in the presence of these drugs." (PMID 25344914, 2014). "Interestingly, both groups of melanoma cell lines, those containing BRAFV600E and those wild-type for BRAF, showed significant inhibition of cell division following vemurafenib treatment compared to controls, although the inhibitory effect was most pronounced in the BRAFV600E lines." (PMID 25557167, 2014). "In addition, our results support the notion that inhibition of autophagy may improve the therapeutic efficacy of inhibitors of BRAF and MEK in the treatment of melanoma." (PMID 25365078, 2014).
melanoma (continued). "Besides BRAF/MEK pathway, other molecular processes are determinant for melanoma onset and progression, and might mediate intrinsic or acquired resistance to BRAF/MEK inhibitors." (PMID 24920406, 2014). "However, not all melanoma patients respond to these therapies and in the case of BRaf inhibitors, the development of acquired resistance has been associated with alternative signalling pathways, including SRC kinase signalling." (PMID 25594008, 2014). "Similarly, mTORC1 activation predicts responsiveness to RAF or MEK inhibitors in BRAF-mutant melanoma; in tumors that do not respond, pRPS6 remains activated and combining mTORC1 inhibition with RAF or MEK inhibition induces a cytotoxic response." (PMID 25228590, 2014). "NF1-mutant melanomas are unlikely to respond to standard BRAF-targeted therapies but may benefit from drugs targeting the MEK and PI3K pathway instead." (PMID 25026295, 2014). "The combinatorial treatment using a BRAF followed by a MEK inhibitor in melanoma patients, though lacking a significant difference in progression free or overall survival compared to monotherapy, came with a partial or, in some cases, even complete response of the patients (NCT01584648)." (PMID 25361007, 2014). "Indeed, over 50% of melanoma patients have tumors with WT BRAF, and therefore do not respond to therapy against this target." (PMID 25057921, 2014). "Given widespread activating mutations in BRAF and, in particular, inability of Spry2 to attenuate ERK in the context of BRAFV600E mutation, their findings argue for a role of Sprouty in regulation of melanoma aggressiveness independent of attenuation of ERK." (PMID 24744103, 2014). "Similarly, mutations of BRAF and NRAS found with high frequency in melanoma seem not to result from the UV irradiation." (PMID 23887651, 2013). "Indeed, the median overall survival of patients with stage IV or advanced melanomas not treated with BRAF inhibitors is only six to 10 months." (PMID 24119386, 2013). "Notably in our studies there was none or only minimal apoptosis in BRAFV600E mutant and WT melanoma cell lines after 48 h of MEK or BRAF inhibition." (PMID 24194739, 2013). "However a currently recruiting, phase II clinical trial (NCT01519427) will be investigating the efficacy of a combination of Selumetinib and the AKT inhibitor MK2206, for BRAF positive stage III and/or IV melanoma patients who had previously relapsed whilst on Vemurafenib or Dabrafenib treatment." (PMID 23515890, 2013). "MEK inhibitors have been unsuccessful both in preclinical models and in patients with resistance to BRAF inhibitors suggesting that other compensatory pathways would be involved and, to date, no effective therapy that circumvents melanoma resistant to BRAF inhibitors is available." (PMID 24161908, 2013). "Importantly, ErbB3 activation is fully abrogated by the simultaneous use of anti-ErbB3 monoclonal antibodies, which are also shown to potently synergize with BRAF inhibitors in the inactivation of both AKT and ERK pathways and in the inhibition of melanoma cell growth." (PMID 23890105, 2013). "Brn3a, however, was very frequently expressed even in early stage melanoma cell lines, but absent in nevi and may be important to attenuate BRAF-induced senescence." (PMID 23666755, 2013). "This hypothesis should prompt experimental studies that analyze the mechanisms of AKT activation in melanoma brain metastases and clinical studies that investigate combinations of PI3K/AKT inhibitors with BRAF/MEK inhibitors or other anticancer agents for treatment of melanoma brain metastases." (PMID 24133630, 2013). "However, an overexpression of KIT and CDK4 has been identified in a subgroup of cutaneous malignant melanomas and would be a mechanism of potential oncogenic transformation of nonmutated BRAF or NRAS melanomas." (PMID 24416617, 2013).
melanoma (continued). "Previously we have shown that AXIN1 levels are regulated by the ERK/MAPK signaling pathway in melanoma, and that depletion of AXIN1 by siRNA-mediated knockdown significantly sensitized multiple melanoma cell lines to apoptosis when treated with a targeted small molecule inhibitor of oncogenic BRAF." (PMID 23869245, 2013). "Mutant BRAF might therefore be a useful therapeutic target in the metastatic lesions of stage III melanoma patients for this reason, as compared to those patients with a localized melanoma of stage IIB-C." (PMID 23951556, 2013). "Similar to the RAS/BRAF/MAPK signaling activation, down-regulation of STAT3 by lentiviral shRNA in STAT3-activated melanoma resulted in inhibition of multiple immunosuppressive cytokines, including IL-6, IL-10, and VEGF, indicating that STAT3 inhibitors may also be useful for immunotherapy." (PMID 23755373, 2013). "Cross presentation may be one of the mechanisms mediating the synergy observed with ACT and BRAF inhibition in melanoma mouse models, although no direct evidence was provided in the reported studies." (PMID 24194739, 2013). "However, since tumors are inherently heterogeneous, investigating the effects of BRAF and MEK inhibition on FDG uptake in a panel of different melanomas could help interpret imaging outcomes." (PMID 22651703, 2012). "Besides frequent mutations in growth- and survival-promoting genes like BRAF and NRAS, melanomas additionally harbor complex non-random genomic alterations." (PMID 22535842, 2012). "This could indicate that the disease progression to leptomeninges was due to the development of drug resistance in BRAF mutated cells (for example, through a switch to the CRAF signaling pathway) and not to the appearance of a different melanoma brain clone." (PMID 22594466, 2012). "This is consistent with the hypotheses that either sorafenib does not effectively inhibit BRAF in melanoma or that one of the other effects of sorafenib, such as CRAF inhibition, counters any RAF inhibitory effect that is achieved." (PMID 21750549, 2011). "However, the expression level of MITF in melanomas is significantly lower than that in normal melanocytes, and higher expression level of MITF in melanoma represses cell proliferation even in the presence of oncogenic BRAF." (PMID 22046555, 2011). "However, in the recent clinical trial of the BRAF inhibitor, vemurafenib (PLX4032), a significant percentage of BRAF V600E mutant melanoma patients did not meet the RECIST criteria for a response." (PMID 21505227, 2011). "Even in NRAS or BRAF mutant melanomas, no reduced function or expression of the DNA repair system could be found." (PMID 22007305, 2011). "Growth inhibition assays on SKMEL28 and CHL-1 cells showed no major differences in the potency of 17-AAG between the two cell lines, consistent with previous studies in larger panels showing that mutant BRAF is not a predictive marker for sensitivity to Hsp90 inhibitors in human melanoma cell lines." (PMID 21037799, 2010). "Moreover, a recent in vitro study showed that simultaneous knockdown of BRAF and expression of CDKN2A in melanoma cells led to potent growth inhibition and apoptosis, whereas knockdown of BRAF or expression of CDKN2A alone did not." (PMID 20140953, 2010). "A recent phase II clinical study reported a lack of activity of 17-AAG in melanoma which may be attributed to the treatment dose and schedule not achieving sustained depletion of BRAF/CRAF kinases." (PMID 21037799, 2010).
melanoma (continued). "Importantly, no strong binding of BRAF to CRAF was seen in A375 cells even in the presence of PD184352 and the drugs did not induce strong BRAF binding to CRAF in two other BRAF mutant melanoma cell lines." (PMID 20141835, 2010). "In addition, the BRAF-inhibitors induced about 30% increase in the proliferation of established carcinoma cells (but not melanoma cell lines) derived from different tumors." (PMID 20149136, 2010). "Regardless of BRAF V600E mutational status, virtually all melanomas have activity in the MAPK pathway, and this contributes to the oncogenic phenotype of melanoma through its effects on cell proliferation, invasion and survival." (PMID 19156138, 2009). "Targeting both the RAS-effector arms, either by combined BRAF and PIK3CA or MEK1+2 and PIK3CA together, effectively delayed the tumor growth confirming the importance of both the PI3K and RAF effector arms in the IPC298 NRAS-mutant melanoma line for tumor growth." (PMID 19492075, 2009). "Therefore, regardless of BRAF mutations, treatment with targeted therapies or chemotherapeutic agents for melanoma increases FAO as a defense mechanism, thereby increasing ATP production and significantly supporting melanoma survival." (PMID 41155168, 2025). "Our hypothesis is also further reinforced by published reports in BRAFV600E melanoma that showed activation of the SRC pathway by Aryl hydrocarbon Receptor (AhR) promotes the acquisition of an invasive and aggressive phenotype resistant to front-line BRAF inhibitors." (PMID 40481178, 2025). "However, treatment with the BRAF inhibitor encorafenib plus the MEK inhibitor binimetinib provided only a seven-year 21.2% PFS and 27.4% OS in 192 patients with unresectable or metastatic BRAF-mutant melanoma who were treatment-naïve or had progressed on first-line immunotherapy." (PMID 40904502, 2025). "However, our PAK RNAi experiments suggest that inhibiting PAK1 alone may not be sufficient to overcome BRAFi/MEKi resistance in BRAF V600-mutant melanoma." (PMID 41109929, 2025). "This suggests that the T cells induced by BRAF/MEK inhibition in melanoma tumors are not conducive to a heightened anti-PD-1 response and may not be tumor-specific but rather a non-specific immune response to cell death induced by the BRAF-targeted therapy." (PMID 38907159, 2024). "Thus, our data may reveal an interesting new treatment strategy for patients with cutaneous BRAF-WT melanoma who do not respond to current standard therapy." (PMID 38263136, 2024). "Furthermore, the POLARIS phase II study (ClinicalTrials.gov identifier: NCT03911869) evaluated the combination of encorafenib and binimetinib in patients with BRAFV600-mutant melanoma and asymptomatic brain metastases who had not previously received BRAF/MEK inhibitors." (PMID 39582535, 2024). "Therefore, the combination of an ICT antibody and CPI-613/HCQ may be useful for patients with BRAF wild-type melanoma who do not benefit from BRAF and MEK inhibitors." (PMID 38434963, 2024). "To determine whether melanomas that have dysregulation of the MRN complex or ATM may be sensitive to PARP inhibitors, we performed independent knockouts of ATM, NBN, and MRE11 in 2 melanoma cell lines, MeWo (TWT) and A375 (BRAF-mutant), followed by olaparib cell viability assays." (PMID 38758740, 2024). "However, no clinically effective RTK combination in BRAF-mutant melanoma has been identified." (PMID 39001489, 2024). "This antibody detects the BRAF V600E mutant epitope with sufficient sensitivity and specificity, as has been demonstrated in several tumor types such as colorectal carcinoma, papillary thyroid cancer and melanoma However, it is not applicable to V600D/K/R or class II and III non-V600E mutations." (PMID 38953007, 2024). "However, the story soon became more complicated when it was found that it was oncogenic BRAF (but not BRAF inhibition) that induces chronic ER stress that could sensitize melanoma to apoptosis." (PMID 36670319, 2023).